BDNF (brain derived neurotrophic factor)
Diseases named in the same sentence as BDNF in open-access papers (continued):
Sharing a sentence is not in itself a finding about the gene and the disease.
Cognitive impairment (continued). "The results of the present study clearly demonstrate that GEGR induces neuroprotective effects in the brain, including the protection of cognitive impairment, dysregulation of BDNF-related signaling pathway, and neuronal cell dysfunction induced by SP injection." (PMID 31623364, 2019). "These divergent serum BDNF- cognitive function relationships across BDNF genotypes in smokers may also provide a clue about the unusual finding of higher BDNF levels with more cognitive impairment." (PMID 30659208, 2019). "Various previous studies have also reported that administration of LPS leads to significant reduction of BDNF mRNA and protein expression in hippocampus and different cortical regions resulting in depressive like sickness behavior and cognitive impairments in these animals." (PMID 31416451, 2019). "Furthermore, BDNF Val66Met genotype groupings had a significant impact on the relationship between BDNF levels and cognitive impairments in smokers." (PMID 30659208, 2019). "BDNF plays a fundamental role for learning and memory and is generally downregulated or not correctly truncated in several neurological diseases characterized by cognitive impairment." (PMID 31614739, 2019). "BDNF levels are also reduced in plasma of patients with mild cognitive impairment (MCI) and AD." (PMID 30117106, 2019). "Thus, BDNF has been proposed to function as a biomarker of cognitive deficit and a therapeutic parameter of cognitive improvement in SCZ patients." (PMID 31098654, 2019). "Since some cognitive domain impairments existed in smokers, we explored whether the cognitive impairments may be related to serum BDNF levels and whether such relationships differed between genotype groupings in smokers." (PMID 30659208, 2019). "Our findings suggest that methylation of BDNF may contribute to the persistent cognitive deficits observed in MDD patients." (PMID 31636250, 2019). "Moreover, SC and RF prevented cognitive impairment via BDNF signaling pathway in a scopolamine-induced rat model." (PMID 31547274, 2019). "BDNF function is a key regulator factor for the cognitive deficits of HD." (PMID 30881980, 2019). "Given that PND is considered a long-term cognitive impairment, BDNF downregulation induced by H3K9 trimethylation might be the main cause of impairment of memory formation after anaesthesia and surgery." (PMID 31708739, 2019). "It was reported that stimulation at GV20 could alleviate the cognitive deficit and exert neuroprotective effects via modulation of the expression and processing of brain-derived neurotrophic factor in mice." (PMID 30744676, 2019). "Similarly, studies of rTMS in cognitive impairment and dyskinesia after stroke have shown that rTMS has an effect on the BDNF‐TrkB receptor pathway in the brain." (PMID 30609300, 2019). "Taken together, these results indicate that the anti-oxidant activity of GEGR contributes to improving the neuronal cell function and survival during cognitive impairment in the SP-induced model through regulation of BDNF secretion and their receptor signaling pathway." (PMID 31623364, 2019). "We propose that the examination of these confounders, whether regarding the individual and/or synergistic effects on peripheral BDNF, might be the “holy grail” of the field examining BDNF and cognitive disorders." (PMID 30634650, 2019). "Therefore, elucidating the direction of changes in peripheral BDNF levels in the spectrum of cognitive impairment from HC to MCI to AD is of dire importance." (PMID 30634650, 2019). "In recent years, some studies demonstrated that different members of the flavonoids family could improve cognitive deficits possibly through elevation of BDNF." (PMID 31763218, 2019).
Cognitive impairment (continued). "To confirm the anti-oxidant activity and BDNF recovery effects of GEGR before analyzing the molecular mechanism on alleviation of cognitive impairment, we determined the free radical scavenging activity, the inhibitory effects against ROS production and BDNF secretion in B35 cells." (PMID 31623364, 2019). "Glycemic improvements as a result of EMPA treatment have been demonstrated to ameliorate cognitive impairment, attenuate oxidative stress and inflammation, and significantly increase brain-derived neurotrophic factor (BDNF) in cerebral tissues of T2DM db/db mice." (PMID 30866531, 2019). "Aging is characterized by a decrease in BDNF concentrations, which suggests that the retrieval of BDNF levels could have a significant impact on the salvage of cognitive impairment." (PMID 30618722, 2018). "Interestingly, our finding was confirmed by a subsequent study showing significant association between cognitive impairment and low BDNF levels in T2DM patients, suggesting that BDNF plays an important role in cognitive impairment in T2DM patients." (PMID 29423073, 2018). "Moreover, serum BDNF levels fall significantly in progressive cognitive decline, e.g., mild cognitive impairment, Alzheimer’s disease, Huntington’s disease, and schizophrenia." (PMID 30542371, 2018). "The principal finding of the present study is that repeated, but not single, exposure of fetal rats to sevoflurane in the second trimester induces long-term cognitive impairment that is accompanied by decreased histone acetylation and reduced levels of BDNF in fetal brain tissue or hippocampus." (PMID 29773978, 2018). "In this study, we hypothesized that fucosterol from Ecklonia stolonifera (E. stolonifera) could regulate sAβ1-42-induced cognitive impairment via BDNF-mediated suppression of ER stress in the dorsal hippocampus of aging rats." (PMID 30301140, 2018). "Cognitive impairment observed in central nervous system diseases suggests that BDNF may be a potential biomarker candidate as its effect has been implicated in learning and memory." (PMID 30233298, 2018). "The standardized regression coefficient “β” suggests that BP equivalent dosage had the greatest influence on cognitive impairment, followed in order by serum BDNF concentration, estimated full-scale IQ, years of education, CP equivalent dosage, age, and ManS total score." (PMID 29896133, 2018). "Thus, small litter size induced cognitive impairment in NMRI mice is associated with higher levels of IL-1β and lower levels of BDNF in the hippocampus." (PMID 30050150, 2018). "A protocol of cognitive rehabilitation such as a 1-month 12-session treatment (three sessions a week) which focuses on the training of executive functioning increased BDNF levels in serum of PD patients affected by mild cognitive impairment, with improved cognitive performance." (PMID 30463271, 2018). "Therefore, plasma BDNF levels can be a potential marker of cognitive impairment induced by Mn exposure." (PMID 30068329, 2018). "Similarly, a 5 consecutive day intraperitoneal (ip) administration of curcumin, a major polyphenol from Curcumalonga, ameliorated cognitive deficits in rats induced by an icv injection of Aβ, via the upregulation of BDNF and activating MAPK pathway." (PMID 30463271, 2018). "Our results confirmed that disruption of the BDNF/TrkB pathway and downstream Akt signaling cascades not only contributed to sevoflurane-induced cognitive impairments but also played an important role in mediating the beneficial effects of maternal exercise on cognitive function in offspring rats." (PMID 29773978, 2018). "Interestingly, there was a notable increase in plasma hcy level and significant decrease in serum BDNF level in amnestic mild cognitive impairment patients that converts to AD patients, especially in those with the APOE ε4 allele." (PMID 30172984, 2018).
Cognitive impairment (continued). "The association between decreased plasma concentrations of BDNF and the degree of cognitive impairment in BD-II patients appears to be independent of the presence of the BDNF Val66Met polymorphism." (PMID 30542371, 2018). "On the other hand, the regulation of BDNF expression could relieve the neurotoxicity of Aβ, enhance synaptic plasticity and improve cognitive impairment." (PMID 29973282, 2018). "Previous studies have suggested that cognitive impairment could be the result of a reduction in the expression of brain-derived neurotrophic factor (BDNF) and/or immune dysfunction." (PMID 29494605, 2018). "The oxidative stress observed in Aβ1–42-induced cognitive disorders decreases BDNF expression." (PMID 29137190, 2017). "More importantly, it is also reported that the decreased BDNF may be involved in cognitive impairment during acute high altitude hypoxia in human volunteers." (PMID 28355243, 2017). "Because the PI3K/Akt signaling pathway is activated by BDNF, our results suggested that SM70EE inhibits phosphorylation of GSK-3β by activating the BDNF/PI3K/Akt signaling pathway in mouse hippocampus to ameliorate the cognitive impairment induced by the I.C.V. injection of Aβ1–42." (PMID 29137190, 2017). "As exception, the protocatechuic acid (3,4-dihydroxybenzoic acid), was shown to modulate inflammation via modulation of BDNF, resulting in amelioration of cognitive deficits, as well as to attenuate amyloid deposits in aged AβPP/PS1 double transgenic mice (100 mg/kg/day during 4 weeks)." (PMID 28352628, 2017). "Furthermore, the importance of BDNF genotype, by modulating the effect physical exercise has on BDNF secretion was also shown in patients suffering from mild cognitive impairment." (PMID 29217995, 2017). "In rats with cognitive impairment, the levels of BDNF decreased in the hippocampus and EE exposure could up-regulate the decreased protein levels of BDNF." (PMID 28360996, 2017). "In the view of cognitive impairments and the marked changes in serum BDNF existed in heroin-dependent patients, and the important implication of BDNF in cognitive function, it would be of interest to explore the association between cognitive deficits and serum BDNF levels in heroin addiction." (PMID 28403087, 2017). "Experiments assessing whether strategies that increase BDNF signaling compared to its basal level may be sufficient to rescue the cognitive impairment in Ts65Dn mice are worthwhile in view of the possible translation to patients with DS." (PMID 29203796, 2017). "In conclusion, vitamin D level, telomere length, and BDNF could act as neuroprotective factors for mild cognitive impairment." (PMID 29109736, 2017). "Also, we measured AChE activity to investigate the relation between cognitive deficits and BDNF/CREB signaling cascades." (PMID 28817076, 2017). "We next evaluated BDNF expression in the hippocampus of adult patients with DS (13–39 years old) prior to the development of an obvious Alzheimer’s neuropathology to obtain insights into the possible translational applicability of a BDNF-mimetic strategy as a treatment for cognitive impairment." (PMID 29203796, 2017). "Therefore, in the present study we aim to explore the link among COX2, BDNF and cognitive deficits in CUMS-exposed rats." (PMID 28415673, 2017). "Impaired expression of BDNF could also be a possible reason for the cognitive deficits in some MG patients." (PMID 28045063, 2017). "BDNF is known to play an important role in the regulation of learning and memory, and can be used as a therapeutic agent to alleviate cognitive impairment." (PMID 28676756, 2017). "Interestingly, it has been observed that lower levels of BDNF in the plasma and the cerebrospinal fluid were presented in the early stages of AD and mild cognitive impairment (MCI)." (PMID 28218653, 2017).
Cognitive impairment (continued). "Hence, this pilot study was designed to investigate the changes of plasma BDNF levels and self-perceived cognitive impairment in ESBC patients receiving chemotherapy." (PMID 29258453, 2017). "In vivo, engrafted BDNF-NSCs-derived neurons not only displayed the Ca2+-response fluctuations, exhibited electrophysiological properties of mature neurons and integrated into local brain circuits, but recovered the cognitive deficits." (PMID 27264956, 2016). "In rodents, for example, an age-dependent decrease of neurotrophic factors, such as the brain-derived neurotrophic factor (BDNF), might contribute to age-related cognitive impairments." (PMID 27458371, 2016). "Some studies reported the correlation between stress and cognitive impairment or BDNF." (PMID 27919226, 2016). "Indeed, BDNF plays a critical role in neuronal survival, synaptic plasticity, and memory, all of which are related to AD-related cognitive deficits." (PMID 26114940, 2015). "Altogether these findings suggest that BDNF serum levels may not only be a trait that characterizes dopaminergic dysfunctions in PD patients but could also be a potential biomarker of their cognitive deficits." (PMID 26441580, 2015). "This study was performed to investigate whether a cognitive rehabilitation protocol focused on the training of shifting abilities was able to alter BDNF serum levels in PD patients affected by mild cognitive impairment." (PMID 25852518, 2015). "Furthermore, the overexpression of BDNF in the hippocampus of Aβ-injected rats mimics the effect of curcumin on cognitive impairments, which can be blocked by ERK inhibitor." (PMID 26114940, 2015). "With regard to neurological disorders, recent data suggest that individuals with Parkinson’s disease (PD) may be affected by cognitive deficits and that they have altered BDNF production." (PMID 26441580, 2015). "Peripheral BDNF levels arealso significantly decreased in people with mild cognitive impairment." (PMID 25162472, 2015). "One hypothesis suggests that a reduced endogenous BDNF expression alters synaptic plasticity and thereby contributes to cognitive impairment in AD." (PMID 25849905, 2015). "Together, our data suggest that the up-regulation of BDNF in the hippocampus via activation of the ERK signaling pathway can ameliorate Aβ1-42-induced learning deficits, thus identifying a novel pathway through which BDNF protects against AD-related cognitive impairments." (PMID 25849905, 2015). "Given the significance of BDNF in the HD brain, we are suggesting that the high-passage mouse BM MSCs were better suited towards delaying the onset of both motor and cognitive deficits in an aggressive mouse model of HD due to significantly higher mRNA expression of BDNF in vitro." (PMID 25971780, 2015). "Interestingly, cognitive impairment and emotional alterations reported in both obese DIO mice and db/db mice are also associated with reduced BDNF levels in the cortex and the hippocampus." (PMID 26190966, 2015). "It is possible to quantify BDNF levels from patient blood samples, so future studies could consider attempting to correlate changes in peripheral levels of BDNF with exercise therapy to improvements in cognitive deficits and mood." (PMID 25806005, 2015). "In conclusion, NPAS4 may be an important regulatory transcription factor in the cognitive impairment process, which directly or indirectly affects cognitive function via BDNF." (PMID 24669275, 2014). "In addition, the positive correlation with BDNF production and attenuation of cognitive decline exemplified that HupA treatment augmented BDNF content and subsequently attenuated cognitive impairment in a mice model with cerebral ischemia-reperfusion injury." (PMID 24857910, 2014). "BDNF level could diminish the progression of patients with mild cognitive deficits and decreased BDNF was previously reported to exacerbate hippocampal damage during DACD." (PMID 24857910, 2014).
Cognitive impairment (continued). "As an MCI predictor, BDNF may be less relevant for early classification (as in this study) than for later cognitive impairment." (PMID 25249975, 2014). "Additionally, BDNF is neuroprotective against brain injury and increase of BDNF is related with enhancement in aging dependent cognitive impairment." (PMID 25359614, 2014). "It was found that downregulation of BDNF expression may contribute to the isoflurane-induced cognitive impairment of these rats." (PMID 25009603, 2014). "Moreover, cognitive impairment and emotional alterations reported in DIO and genetic models of obesity are linked to increased inflammation and reduced BDNF levels in the cortex and the hippocampus." (PMID 24860551, 2014). "Plasma BDNF levels are associated with cognitive impairment in FEP patient but not in healthy controls." (PMID 23320462, 2013). "Our imaging-genetics analysis in a large dataset suggests that BDNF genetic variation may play a role in AD-related cognitive deficits as well as brain neurodegeneration." (PMID 24086677, 2013). "These cognitive impairments were not accompanied by decreased levels of BDNF in brain tissue and neither did they seem to be caused by circulatory inflammation." (PMID 24223947, 2013). "However, a higher local level of GC probably contributes to the cognitive impairment and the impairment of the memory form by suppressing the hippocampus BDNF expression, which is a neurotrophic factor." (PMID 22792090, 2012). "Furthermore, improvements were also seen in aged primates, where BDNF gene delivery to the entorhinal cortex reversed neuronal atrophy and ameliorated age-related cognitive impairment." (PMID 22654716, 2011). "Such hypothesis has been substantiated by a recent study indicating that deficits of synaptic Zn2+ promotes AD-like cognitive impairment by negatively interfering with glutamatergic and BDNF signalling." (PMID 21423579, 2011). "Studies in schizophrenia show that RELN hypermethylation reduces reelin expression and disrupts synaptic plasticity and neuronal migration; COMT methylation alters dopamine metabolism; and BDNF methylation is associated with cognitive impairment and negative symptoms." (PMID 41234420, 2025). "Additionally, it was observed that MHD patients with cognitive impairment exhibited significantly lower levels of brain-derived neurotrophic factor (BDNF) and platelet counts (PLT) in comparison with both healthy controls and individuals with normal cognitive function." (PMID 40950978, 2025). "Additionally, DPP4 inhibitors may protect against the progression of cognitive disorders in diabetic individuals by increasing neurotrophin levels, such as BDNF, NGF, and NT-4, promoting neuronal growth, survival, and synaptic plasticity." (PMID 38860903, 2025). "However, to confirm this hypothesis, future studies could use techniques such as BDNF gene knockdown or overexpression in the context of PTX-induced cognitive impairment models." (PMID 40322465, 2025). "Total scores on MMSE and CDT clinical scales used for assessing the cognitive deficits were similar among patients carrying different BDNF Val66Met genotypes, indicating a lack of association of BDNF Val66Met polymorphism and cognitive decline in individuals with MCI and dementia." (PMID 41009553, 2025). "Furthermore, Cu may impair synaptic plasticity by mediating cuproptosis and inhibiting the cAMP response element-binding protein (CREB)/brain-derived neurotrophic factor (BDNF) signaling pathway, ultimately leading to cognitive deficits in mice." (PMID 41158661, 2025). "Importantly, genetic or pharmacological interventions that increase BDNF levels have been shown to alleviate some of the motor and cognitive deficits in these models, suggesting that enhancing BDNF signaling could be a viable therapeutic strategy." (PMID 40005159, 2025).